EGFR (epidermal growth factor receptor)
Diseases named in the same sentence as EGFR in open-access papers (continued):
Sharing a sentence is not in itself a finding about the gene and the disease.
tumor (continued). "Adding cetuximab to vemurafenib in xenografts experiments resulted in increased antitumor activity and improved survival and combined administration of BRAF and EGFR inhibitors induces tumor regression in most patients." (PMID 35582524, 2022). "The combination of YTHDF1 silencing and EGFR inhibition dramatically inhibited HCC tumor metastasis after inadequate radiofrequency ablation in vivo, suggesting YTHDF1 as a potential therapeutic target for metastatic HCC." (PMID 35884552, 2022). "The epidermal growth factor receptor (EGFR) is a tyrosine kinase in the cell membrane of many tumor types." (PMID 35409325, 2022). "In a previous report, the Ru(II)-arene complex [Ru(η6-p-cymene)Cl2] (RAPTA-C) was tested for efficacy in combination with the epidermal growth factor receptor inhibitor erlotinib, demonstrating an efficient anti-angiogenic and anti-tumor activity." (PMID 36362089, 2022). "In Ephrin receptors, EFNA4 was conserved in EGFR-mut and KRAS-mut tumor while EFNA3 was conserved in EGFR-mut and NEK tumors." (PMID 36612014, 2022). "Substantial decrease in lysosomal sequestration was predicted for both strong basic EGFR-TKIs in the less lysosome-rich tumor in comparison with lung tissue." (PMID 35890095, 2022). "The addition of gefitinib to the group of knockdown of GPER1 further inhibited tumor growth, with a synergistic inhibitory effect on the tumor growth between inhibition of GPER1and EGFR pathways." (PMID 35664735, 2022). "A series of phase II clinical trials reported that neoadjuvant treatment with EGFR-TKIs significantly reduced tumor volume, improved radiologic response, and increased radical surgical resection rates." (PMID 36467102, 2022). "NGS analysis revealed that a subset of the NF-κB/RELA target genes was synergistically suppressed, and expression levels of a series of tumor suppressor genes were elevated by the co-targeting EGFR and IKK with specific small molecule inhibitors." (PMID 36358633, 2022). "Downstream kinases of EGFR, including (but not limited to) the mitogen‐activated protein kinases (MAPKs) and PI3K‐Akt, are always hyperactive because of abnormal auto‐phosphorylation of EGFR in tumor tissue." (PMID 35748027, 2022). "Beyond BIM modulation, how EGFR-mutant tumor cells regulate the apoptotic response during EGFR-targeted therapy remains incompletely defined." (PMID 35579943, 2022). "Preclinical studies have shown that the combination of HER2 and EGFR blockade can lead to CRC tumor regression." (PMID 35740594, 2022). "This tumor-suppressive cell competition restrains EGFR and Hippo signaling and enables Eiger-JNK mediated apoptosis in scrib−/− clones." (PMID 36271083, 2022). "TKIs work to inhibit improper activity of EGFR, which is involved in both cell apoptosis and tumor progression." (PMID 36290844, 2022). "used exosomes to deliver let-7a miRNA, which was transferred and internalized to epidermal growth factor receptor (EGFR)-expressing in tumor tissues, exhibiting extraordinary tumor therapeutic effects." (PMID 35574366, 2022). "GLUT1 acts on tumor cells via a number of downstream signaling pathways, including the EGFR/ERK/PKM2 and integrin 1/Src/FAK signaling pathways." (PMID 35712514, 2022). "This allows EGFR to trigger downstream signalling pathways in a growth factor-independent dysregulated fashion, ultimately eliciting uncontrolled cell division and tumour proliferation." (PMID 35158954, 2022). "EGFR is often expressed at high levels in different cancers, and its expression positively correlates with tumor progression and poor prognosis." (PMID 36349315, 2022). "A bispecific antibody that inhibits PD-1 and EGFR (anti-PD-1 x anti-EGFR) has been shown to significantly suppress tumor growth and activate antitumor immunity in animal models of various types of cancer." (PMID 36012588, 2022).
tumor (continued). "An improved knowledge of the mechanisms involved in colorectal carcinogenesis and tumor progression has allowed the development of biological agents with targeted actions, as inhibitors of angiogenesis, EGFR-targeted therapy, and immunotherapy." (PMID 36011003, 2022). "After two days of co-culture with EGFR CAR T cells, resistant clones of tumor cells were enriched for loss of genes involved in IFNγ-mediated signaling, such as IFNGR1 and JAK1." (PMID 36189315, 2022). "A total of 19 different EGFR mutations were identified in 88% (44 of 50) ISP and 77% (17 of 22) ISP-associated SNSCC tumours." (PMID 35053553, 2022). "Expression of AXL and CDCP1 in tumor samples was examined by immunohistochemical (IHC) analysis after tumors were surgically resected in 6 patients (#1, #2 with wild-type EGFR; #3, #4 with EGFRdel19; #5, #6 with L858R EGFR) before chemotherapy." (PMID 35643725, 2022). "The resulting imaging revealed that MIP-target HeLa cells (high-expression EGFR) glow more brightly than MIP-target MCF-7 cells (low-expression EGFR), indicating that the C-MIP targets tumor cells that overexpress EGFR." (PMID 35265217, 2022). "Targeted next-generation sequencing (NGS) was performed on DNA extracted from the tumor biopsy specimen, revealing that the tumor harbored EGFR exon 19 deletion." (PMID 35747829, 2022). "Nevertheless, our study is one of the few real-world studies that specifically addressed the effect of primary tumor location on the clinical outcomes of patients with KRASwt mCRC that were treated with anti-EGFR Ab therapy as second- or later-line treatment." (PMID 35242708, 2022). "Recently, IT effectiveness was shown to correlate positively with the number of CD8+ lymphocytes and negatively with the number of FOXP3+ tumor-infiltrating lymphocytes in patients who acquired resistance to EGFR-TKIs." (PMID 35742933, 2022). "Tumor genotyping has now been incorporated in the clinical management of NSCLC with routine testing for EGFR, KRAS, BRAF, HER2, ALK, ROS-1, and RET to personalize first or second-line treatment." (PMID 35267628, 2022). "The TNF-related apoptosis-inducing ligand (TRAIL) and control of EGFR downstream signaling, together with the overexpression of the epidermal EGFR in some tumor cells, have substantial effects on inducing apoptosis in tumor cells." (PMID 36559102, 2022). "Compared to tumor tissue, the detection rates of actionable EGFR in CSF were significantly higher than those in tissue samples in both the CNSM and CNSM+ groups (all p <0.001)." (PMID 35814426, 2022). "Mechanically, the nano‐TriKEs allowed spatiotemporal regulation on the engagement of NK cells and tumor cells by specifically targeting EGFR‐overexpressing tumor cells and potentiating NK‐cell activation via CD16 and 4‐1BB receptors." (PMID 36257824, 2022). "MiR-133b has been proved to function as a tumor suppressor by regulating EGFR in several human cancer types, and it is significantly dysregulated in tumors such as CRC, prostate cancer and lung cancer." (PMID 36131281, 2022). "In EGFR TKI-resistant tumor models, forced miR-483-3p expression via a lentiviral vector observably stimulated gefitinib sensitivity, showing its potential as a therapeutic agent." (PMID 36139582, 2022). "Taken together, the authors believe that a combination therapy using anti-TMEM16A and anti-PD-L1 inhibitors can be a promising strategy to improve the survival rate of HNSCC, particularly when the tumor gains resistance to anti-EGFR inhibitor treatment." (PMID 35668455, 2022). "In an immunocompetent model, OV-IL15C plus EGFR-CAR NK cells synergistically inhibited tumor growth and markedly increased survival compared to either monotherapy." (PMID 36703982, 2022). "While PI3K targeting kills liver-colonising CR-CSCs, the concomitant inhibition of PI3K, HER2 and MEK is required to induce regression of tumours resistant to anti-EGFR therapies." (PMID 33436496, 2022).
tumor (continued). "Our work proposes a bifurcate recycling mechanism for EGFR and its inhibitor Ptp10D in epithelial cells during tumor-suppressive cell competition." (PMID 36271083, 2022). "Tumor 11C-erlotinib uptake in NSCLC patients after erlotinib therapy was reduced and further illustrated the 11C-erlotinib binding specificity of EGFR mutation." (PMID 36276079, 2022). "It has been reported that mutant EGFR ecDNA is eliminated in tumor cells during TKI treatment, inducing drug resistance, but restores after drug withdrawal." (PMID 34319535, 2022). "Preclinical studies have shown that anti-EGFR therapy induces tumor-specific immune responses and immunogenic apoptosis, while functional adaptive immunity mediates the effect." (PMID 35433839, 2022). "The conjugate, compared to free Ce6, showed increased accumulation in cells with higher levels of EGFR expression, increased phototoxicity, and preferential accumulation in the tumor tissue of tumor-bearing mice." (PMID 35213974, 2022). "EGFR protein overexpression was much higher in metastatic lesions than in primary tumors, with high gene copy numbers indicating tumor progression." (PMID 35978803, 2022). "The developed anti-EGFR immunolipoplexes and immunoviroplexes showed remarkable cell binding and siRNA delivery to EGFR-expressing tumor cells compared with immunoliposomes and immunovirosomes." (PMID 36499115, 2022). "The epidermal growth factor receptor (EGFR) signaling pathway is usually closed in normal tissues but activated and opened in tumor tissues." (PMID 35186080, 2022). "What’s more, this team proposed that acquired resistance to anti-EGFR therapy was a fait accompli and that the timing of the emergence of resistance depended on the time interval required for tumor cell subclones to repopulate the lesion." (PMID 36110958, 2022). "We sampled 132 EGFR WT and 99 EGFR-mutated NSCLC FFPE tumor specimens and found that EGFR mutant cells expressed significantly higher CD73 compared with the WT cells." (PMID 35132961, 2022). "It was found that mice infected with oncolytic vaccinia virus expressing anti-EGFR single-chain antibody (GLV-1h442) show significantly slower tumor growth in vivo than mice infected with empty oncolytic vaccinia virus (GLV- 1h68) alone." (PMID 35371972, 2022). "The results demonstrated CAR-T cell-specific activation that was dependent on the presence of EGFR-expressing tumor cells at the periphery of the tumor islets, which are initially the only ones permissive to CAR-T cell binding." (PMID 35466279, 2022). "RAS mt clones display pulsatile behavior, arising with EGFR blockade and decaying on withdrawal of the anti-EGFR mAb, allowing a tumor to regain sensitivity to the drug." (PMID 36818675, 2022). "The results showed that 60% (252/422) of the tumor tissues had driver mutations, including 107 cases of KRAS (25%), 98 cases of EGFR (23%), 14 cases of ALK rearrangement (6%)." (PMID 35433677, 2022). "Staining with EGFR L858R antibody was clearly seen in tumor sample #12-T (~56% of total EGFR is mutant), and the significant staining of 19del-specific antibody was only found in tumor sample #6-T (~50% of total EGFR is mutant)." (PMID 36376325, 2022). "Maintaining ionic currents is essential for cellular signalling in normal astrocyte function and EGFR-amplified tumours." (PMID 36497413, 2022). "A significant difference between two genotypes occur at stage 1, in which KRAS+ tumor cells displayed more normal nucleocytoplasmic ratios, perhaps due to slightly larger cell size and smaller nuclei compared to EGFR+ cells." (PMID 36201559, 2022). "This can be due to the IGF-1 secretion from HFL1 cells that maintain the tumour cells by preventing the EGFR-related signal pathway by the drug and activating the PI3K/Akt signal pathway." (PMID 37360644, 2022). "On day 13, BLT measurement showed that EGFR CAR T cell treated animals appeared to have two distinct signal peaks matching with tumor and spleen site." (PMID 35836798, 2022).
tumor (continued). "First, TINCR enhances EGFR expression and downstream signaling via regulation of the STAT3–TINCR–EGFR pathway, and acts as a competing endogenous RNA to upregulate EGFR expression by sponging miRNA-503, resulting in tumor growth, proliferation, and migration." (PMID 35159070, 2022). "Small molecular inhibitor erlotinib has been discovered recently, it suppresses tumor growth by inhibiting the activation of EGFR." (PMID 35027542, 2022). "In another study, doxorubicin was used as a template, together with a linear epitope of the epidermal growth factor receptor (EGFR) that is over-expressed in several tumours, to prepare a double-imprinted nanoMIP by solid-phase synthesis." (PMID 35225975, 2022). "The detection of EGFR mutations in ctDNA from NSCLC patients has proved to be complementary to tissue biopsy in clinical practice and is correlated with both the tumor baseline lesion size and response to EGFR TKIs." (PMID 35326725, 2022). "EETs activate the MAPK and PI3K/Akt signaling pathways, enhance EGFR phosphorylation, regulate the tumor microenvironment, and facilitate immunosuppression in a number of tumor cell lines following an autocrine and paracrine manner." (PMID 35990839, 2022). "Surface-modified Au nanoparticles were combined with the EGFR of tumor cells to enable targeted localization." (PMID 35684522, 2022). "Recently, it was found that NSCLC tumor tissues had a higher content of LDs compared with pericancer tissues, which was further increased in tumor tissues of patients who underwent EGFR-TKI treatment." (PMID 35159223, 2022). "Especially, EGFR-TKIs can improve the local control rate, prolong the tumor progression-free stage and the overall survival period, and improve the life quality of these patients." (PMID 36467103, 2022). "There were trends towards increased expression of HOTAIR and EGFR in tumor tissues compared to adjacent normal tissues." (PMID 36471329, 2022). "Early studies have linked EGFR over-expression to radioresistance and demonstrated that EGFR inhibition in combination with IR leads to decreased tumour cell growth." (PMID 36233505, 2022). "The finding that there was little tumor damage in SAS spheroids despite the inhibition of EGFR phosphorylation by cetuximab is probably attributable to the very low basal expression of EGFR in untreated SAS spheroids." (PMID 35928727, 2022). "Our study explores for the first time the innate immune component triggered by osimertinib in the context of targeting HER3 to treat TKI resistance in NSCLC, generating a rationale for trials aiming to improve anti-tumor immunity in mutant-EGFR/NSCLC patients." (PMID 35347108, 2022). "Therapeutically, combination of EGFR-TKI with ACh/M3R signaling inhibition using the FDA-approved drug darifenacin impeded tumor relapse in mice, demonstrating a prospective combination therapeutic strategy to manipulate the emergence of drug tolerance." (PMID 36048538, 2022). "Silicon-coated gold nanoparticles (sized 140 nm) modified with theZEGFR:1907 anti-EGFR affibody through a heterobifunctional maleimidederivative of PEG were used to selectively label a EGFR-overexpressing cellculture and for ex vivo tumor imaging." (PMID 35441046, 2022). "In this study, EGFR ex19del was detected in 6/11 (54%) of pre-treatment tumors, 2/11 (18%) of post-treatment tumors, and 1/11 (9%) of tumor stroma." (PMID 36505794, 2022). "The current literature suggest that neoadjuvant therapy with EGFR-TKIs significantly reduce tumor volume, improve imaging response, and increase radical surgical resection rate, but does not translate into disease downstaging or pathological remission." (PMID 36467102, 2022). "EVs isolated from BALF contain double-stranded DNA and can thus be utilized as an alternative to tumor tissue for EGFR genotyping." (PMID 35681723, 2022). "We examined EGFR expression in both tumor and normal breast TMA and its correlation with FAM83A protein level." (PMID 35183258, 2022).
tumor (continued). "The first demonstration of the anti-tumor response of IgA in vivo was shown in an EGFR model using FcαRI transgenic mice, using both IgA1 and IgA2 EGFR antibodies." (PMID 35865547, 2022). "When Fuc is highly expressed in epidermal growth factor receptor (EGFR), EGFR dimerization and phosphorylation are increased, and EGFR-mediated tumor cell growth and malignancy-related signaling pathways are increased." (PMID 36072925, 2022). "Other studies have demonstrated that growth factors, such as EGF, can also be used as a tumor-targeting moiety on the surface of pHPMA to redirect the Ad internalization of EGFR-positive cells." (PMID 35444290, 2022). "cet.Hum.scFv-IRDye80CW-induced signal intensity in U-87 MG tumor xenografts (100-125 au) was significantly lower than that in EGFR-overexpressing A431 xenografts (278-420 au) (p ≤ 0.05)." (PMID 35517713, 2022). "The benzyl homolog 10 is suggested as a putative dual inhibitor of tubulin and EGFR, displaying good cytotoxic potency in different human tumor cell lines." (PMID 35893736, 2022). "TNBC cell line MDA-MB-231 was subcutaneously injected into the flank region of mice and when tumor volume reached 50–100 mm3, anti-EGFR/PD-L1 BsAbs, cetuximab, atezolizumab or saline was injected in tumor-bearing mice." (PMID 35890277, 2022). "Epidermal growth factor receptor (EGFR) is a key tumour driver and one of the main targets in the successful treatment of NSCLC." (PMID 36439419, 2022). "TGFα is widely expressed in both normal epithelium and tumour cells and it is considered a ligand for EGFR." (PMID 35681586, 2022). "Co-transfection of IL-12 and salmosin genes using anti-EGFR immunolipoplexes significantly reduced tumor growth as well as pulmonary metastasis due to its high binding affinity to the EGFR-positive cancer cells." (PMID 36428682, 2022). "The bispecific T-cell engager (BiTE) was composed of two single chain antibodies (scFV) that targeted the tumour-specific EGFR and CD3 on the T-cell receptor to activate T-cells and bring the complex close to the tumour cell for improved elimination." (PMID 35813830, 2022). "Several phase I studies have shown the potential of EGFR-targeted FMI for intraoperative ex vivo tumor margin assessment in OSCC." (PMID 34531264, 2022). "Strikingly, however, we observed overexpression of ATG16‐L1 Ex8 in the tumors of 3/11 patients at relapse following EGFR‐TKI treatment compared with paired tumor samples before treatment." (PMID 35593080, 2022). "Monoclonal antibody therapy is a treatment option for patients suffering from EGFR-related tumor burden." (PMID 35479092, 2022). "On the other hand, we observed the significant upregulation of the insulin receptor gene (ISNR), which is responsible for stimulation of tumor cell proliferation, migration, and invasion, and can be co-expressed with the EGFR gene in tumors." (PMID 35216085, 2022). "FL‐CAR T cells killed only the EGFR+ MDA‐MB‐468 cells when tumor cell mixture was treated with α‐EGFR‐FL, whereas the EGFR‐ Ramos cells were not killed by FL‐CAR T cells." (PMID 35146940, 2022). "It is to be noted that only these two benzamide derivatives exhibited dual inhibition of HDAC and EGFR along with other tumor cell lines with IC50 in the micromolar range." (PMID 35408693, 2022). "Model evaluation results show that the distribution of the model simulations was also in line with the distribution of the tumor size and concentrations of mutant EGFR obtained from NSCLC patients." (PMID 35273301, 2022). "The EGFR ddPCR assay was also used to detect circulating cell free tumor DNA from patients’ plasma specimens." (PMID 35202431, 2022).